DDX50 (DExD-box helicase 50)
Description:
ATP-dependent RNA helicase that may play a role in various aspects of RNA metabolism including pre-mRNA splicing or ribosomal RNA production. Also acts as a viral restriction factor and promotes the activation of the NF-kappa-B and IRF3 signaling pathways following its stimulation with viral RNA or infection with RNA and DNA viruses. For instance, decreases vaccinia virus, herpes simplex virus, Zika virus or dengue virus replication during the early stage of infection. Mechanistically, acts via the adapter TICAM1 and independently of the DDX1-DDX21-DHX36 helicase complex to induce the production of interferon-beta.
Synonyms: GU2; MGC3199; GUB; RH-II/GuB; mcdrh
Tractability: Antibody: its Gene Ontology location is reachable by antibodies, with high confidence. PROTAC: UniProt records ubiquitination sites on it; ubiquitination databases record sites on it; its protein half-life has been measured.
Gene: Protein-coding gene on chromosome 10 (68,901,264 to 68,946,847, forward strand). Ensembl gene ENSG00000107625.
Subcellular location: Nucleus, nucleolus; Cytoplasm
Subcellular location (Human Protein Atlas): Nucleoli
Gene Ontology:
Molecular function: ATP hydrolysis activity; RNA binding; ATP binding; helicase activity; nucleic acid binding; RNA helicase activity
Cellular component: cytoplasm; membrane; nucleolus
Genetic constraint (gnomAD): Loss-of-function variants: 56 observed, 89.95 expected, observed/expected ratio (o/e) 0.62, 90% interval 0.5 to 0.78. The upper end of that interval is the gene's LOEUF score, 0.78, which puts it in group 3 of 6, group 1 being the genes least tolerant of losing a copy. Missense variants: 680 observed, 849.59 expected, observed/expected ratio (o/e) 0.8, 90% interval 0.75 to 0.85. Synonymous variants: 254 observed, 289.85 expected, observed/expected ratio (o/e) 0.88, 90% interval 0.79 to 0.97.
Homologues: Orthologues: chimpanzee DDX50 (99% identical), macaque DDX50 (99% identical), dog DDX50 (98% identical), guinea pig DDX50 (96% identical), rabbit DDX50 (96% identical), mouse Ddx50 (95% identical), rat Ddx50 (95% identical), pig DDX50 (95% identical). Paralogues in human: DDX21 (60% identical), DDX18 (22% identical), DDX3Y (21% identical), DDX27 (21% identical), DDX3X (21% identical), DDX54 (21% identical), DDX42 (21% identical), DDX46 (20% identical), DDX43 (20% identical), DDX4 (20% identical), DDX41 (20% identical), DDX10 (20% identical), and 26 more.
Diseases named in the same sentence as DDX50 in open-access papers:
DDX50 is named in the same sentence as 4 diseases in open-access papers, as found by Europe PMC text mining. Sharing a sentence is not in itself a finding about the gene and the disease. The quoted sentences say what the papers report.
viral infection (2 papers, 2017 to 2022). "In conclusion, this study identified DExD-Box RNA helicase DDX50 as a crucial component facilitating DDX1-independent IRF3 activation following stimulation with dsRNA or viral infection and further established a pivotal role for DDX50 as a viral restriction factor for RNA and DNA viruses." (PMID 35215908, 2022). "We found that DDX50 might be as a positive regulator of HTNV replication, indicating that DDX50 harbored opposite effects against DDX21 upon viral infection." (PMID 28676847, 2017).
infection (3 papers, 2022 to 2025). The state of being infected such as from the introduction of a foreign agent such as serum, vaccine, antigenic substance or organism. "Following infection with either virus, the effect of Ddx50 KO on Cxcl10 expression, although significant, was less pronounced in comparison to Isg56 and Ifnb." (PMID 35215908, 2022). "Together, these results provide evidence that DDX50 promotes antiviral signalling during infection and is a restriction factor for both DNA and RNA viruses, with its loss resulting in increased viral spread and subsequent replication in tissue culture." (PMID 35215908, 2022). "Using microscopy, we confirmed the prediction of our chaperone interaction analysis, observing colocalization of DDX10, DDX18, DDX50, and GTPBP4 with VICE domains upon infection with HSV-1." (PMID 40577456, 2025). "Deletion of DDX50 in mouse and human cells impaired IRF3 phosphorylation and IRF3-dependent endogenous gene expression and cytokine/chemokine production in response to cytoplasmic dsRNA (polyIC transfection), and infection by RNA and DNA viruses." (PMID 35215908, 2022). "While DDX50 has been described to act as a co‐factor for c‐Jun‐activated transcription, the localization of DDX50 remains unclear, with one study showing DDX50 in the cytoplasm functioning upstream of MAVS and another showing retainment in the cytoplasm following infection." (PMID 39620586, 2025). "While not known to bind viral RNA directly, DDX50 binds TRIF and enhances phosphorylation and activity of both NF‐κB and IRF3 following poly(I:C) transfection or infection with dengue virus (DENV), SeV, HSV‐1, or vaccinia virus (VACV)." (PMID 39620586, 2025). "Here, we describe DDX50, which shares 55.6% amino acid identity with DDX21, as a non-redundant factor that promotes activation of the IRF3 signalling pathway following its stimulation with viral RNA or infection with RNA and DNA viruses." (PMID 35215908, 2022).
DDX50 also shares sentences with these, for which no sentence is quoted: tumours (2 papers); lung carcinoma (1).